DOK7 (docking protein 7)
Description:
Probable muscle-intrinsic activator of MUSK that plays an essential role in neuromuscular synaptogenesis. Acts in aneural activation of MUSK and subsequent acetylcholine receptor (AchR) clustering in myotubes. Induces autophosphorylation of MUSK.
Synonyms: C4orf25; FLJ33718; FLJ39137; Dok-7; CMS10; CMS1B
Tractability: Antibody: UniProt places it where antibodies can reach, with medium confidence; its Gene Ontology location is reachable by antibodies, with medium confidence.
Gene: Protein-coding gene on chromosome 4 (3,463,306 to 3,501,473, forward strand). Ensembl gene ENSG00000175920.
Subcellular location: Cell membrane; Synapse
Subcellular location (Human Protein Atlas): Nucleoplasm; Mitochondria
Gene Ontology:
Molecular function: protein binding; protein kinase binding; phosphatidylinositol binding; signaling adaptor activity
Biological process: positive regulation of protein tyrosine kinase activity; neuromuscular junction development; enzyme-linked receptor protein signaling pathway; positive regulation of Rac protein signal transduction
Cellular component: mitochondrion; nucleoplasm; neuromuscular junction; plasma membrane; postsynaptic membrane; synapse
Genetic constraint (gnomAD): Loss-of-function variants: 34 observed, 27.23 expected, observed/expected ratio (o/e) 1.25, 90% interval 0.95 to 1.66. The synonymous counts are far from expectation, so gnomAD's model fits this gene poorly and the ratio says little. Missense variants: 1,007 observed, 656.43 expected, observed/expected ratio (o/e) 1.53, 90% interval 1.46 to 1.62. Synonymous variants: 447 observed, 298.78 expected, observed/expected ratio (o/e) 1.5, 90% interval 1.38 to 1.62.
Gene-disease validity (ClinGen):
ClinGen rates the evidence that DOK7 causes each of these diseases.
congenital myasthenic syndrome 10 (autosomal recessive): Definitive.
Homologues: Orthologues: macaque DOK7 (88% identical), chimpanzee DOK7 (87% identical), mouse Dok7 (85% identical), rat Dok7 (84% identical), dog DOK7 (81% identical), guinea pig DOK7 (81% identical), tropical clawed frog dok7 (63% identical), zebrafish dok7b (54% identical), zebrafish dok7a (37% identical), Caenorhabditis elegans F14D12.1 (18% identical).
Diseases named in the same sentence as DOK7 in open-access papers:
DOK7 is named in the same sentence as 45 diseases in open-access papers, as found by Europe PMC text mining. Sharing a sentence is not in itself a finding about the gene and the disease. The quoted sentences say what the papers report.
congenital myasthenic syndrome (32 papers, 2010 to 2025). Congenital myasthenic syndrome (CMS) is a group of genetic disorders of impaired neuromuscular transmission at the motor endplate characterized by fatigable muscle weakness. "This mouse model harbours a duplication in the Dok7 gene that corresponds to the mutation most commonly found in DOK7 congenital myasthenia patients, c.1124-1127dupTGCC." (PMID 39944742, 2025). "Although mutations in the downstream of tyrosine kinase-7 (DOK7) are one of the most common causes of congenital myasthenic syndrome (CMS) in children and adults, CMS in adults due to the heterozygous variant c.1399_1404del in DOK7 has not yet been reported." (PMID 40330390, 2025). "In view of this response, the patient was initially diagnosed as suffering from congenital myasthenia, and two mutations in DOK7 were detected." (PMID 38397198, 2024). "We also identified a novel homozygous frameshift deletion (c.1134delG) in exon 7 of the DOK7 gene mutation in PID_108, reportedly linked to the congenital myasthenic syndrome." (PMID 38057384, 2023). "The patient exhibited mutations in DOK7 (downstream of kinase), an adapter protein for MuSK, which is an important cause of congenital myasthenia." (PMID 37303354, 2023). "Genetic studies have revealed that mutations in the SH2 domain of DOK7 contribute to a subgroup of congenital myasthenic syndromes (DOK7-CMS), an inherited neuromuscular disorder characterized by fatigable muscle weakness." (PMID 37637210, 2023). "We identified a patient with congenital myasthenic syndrome (CMS) with two heteroallelic mutations in DOK7, c.653-1G>C in intron 5 and c.190G>A predicting p.G64R in the pleckstrin homology domain." (PMID 36579833, 2023). "DOK7 is associated with congenital myasthenic syndromes, a group of neuromuscular disorders caused by impaired neuromuscular transmission, and encodes an adaptor protein which mediates tyrosine kinase signaling to form the neuromuscular synapse." (PMID 35976950, 2022). "In a mouse model of congenital myasthenia caused by mutations in the Dok7 gene, agonist antibodies against MUSK restore synaptic function and survival." (PMID 34163073, 2021). "Congenital myasthenia (CM) is a devastating neuromuscular disease, and mutations in DOK7, an adaptor protein that is crucial for forming and maintaining neuromuscular synapses, are a major cause of CM1,2." (PMID 34163073, 2021). "Given that mutations in the human Dok7 gene result in congenital myasthenia (Dok7 myasthenia), Dok7 would be required not only for the formation but also for the maintenance of NMJs." (PMID 31181747, 2019). "Components of the LRP4/MuSK/Dok-7 complex are the targets of mutations responsible for subsets of congenital myasthenic syndromes (CMS), which are characterized by fatigable muscle weakness." (PMID 29462491, 2018). "Patients who have mutations in Dok7 develop congenital myasthenic syndrome (CMS) associated with small neuromuscular synapses." (PMID 20565848, 2010). "As an example of gene specific attributes selection in iFish, for the DOK7 gene which is associated with congenital myasthenic syndrome, four attributes including GERP conservation score, hydrophobicity, transmembrane tendency and turn tendency of amino acids were selected." (PMID 27527004, 2016). "Hypomorphic mutations in Dok-7 give rise to a form of congenital myasthenic syndromes (CMS) called limb-girdle myasthenia in humans." (PMID 26527617, 2016). "Mutations in MUSK and genes that act in the MuSK signaling system (including DOK7) induce congenital myasthenia." (PMID 37240968, 2023). "DOK-7 (docking protein 7) controls MuSK activation and response to agrin; mutations in the DOK7 gene are responsible for the congenital myasthenic syndrome, which is characterized by impaired NMJ structure and functionality." (PMID 33801336, 2021).
congenital myasthenic syndrome (continued). "It is worth noting that gene mutations in the agrin-LRP4-MuSK-Dok7-rapsyn-AChR pathway, including the genes AGRN, MUSK, DOK7, RAPSN, cause congenital myasthenic syndromes (CMSs)." (PMID 33328881, 2020). "However, in cases with DOK7 and COLQ mutations and slow-channel congenital myasthenic syndrome, symptoms worsen due to pyridostigmine treatment." (PMID 37766777, 2023). "Consistent with this idea, adenoviral expression of Dok-7, an inside-outside activator of MuSK, not only extends longevity of SOD1-G93A mice but also provides benefit in other mouse models of neuromuscular disease, including congenital myasthenia and Emery-Dreifuss muscular dystrophy." (PMID 29460776, 2018).
breast carcinoma (10 papers, 2016 to 2025). "First, we showed that DOK7 expression was obviously reduced in the breast cancer tissues and lower levels of DOK7 linked to more aggressive behaviors and worse prognosis of patients." (PMID 33552156, 2021). "A recent study of identical twins with differential breast cancer statuses identified DOK7 gene methylation as an indicator of breast cancer risk." (PMID 26884724, 2016). "However, in breast carcinoma, significant DOK7 promoter hypomethylation implicated its role in early tumorigenesis." (PMID 36551712, 2022). "To investigate whether the level of DOK7 is related to the aggressive behavior in breast cancer patients, we analyzed the association between DOK7 levels and different clinical outcomes (TNM stage, tumor diameter, and lymph node metastasis)." (PMID 33552156, 2021). "The clinical relevance of SPDEF methylation is further supported by prior studies using MSRE-qPCR in other cancers (e.g., ITGA6 in breast cancer, DOK7 in gastric cancer)." (PMID 40457266, 2025). "DOK7 inhibits the proliferation, migration, and invasion of breast cancer cells through the PI3K/PTEN/AKT pathway." (PMID 36980850, 2023). "In conclusion, this study displayed that DOK7 was lowly expressed in breast cancer tissues, suggesting that DOK7 was a potential tumor-suppressor gene." (PMID 33552156, 2021). "The results showed that the mRNA levels of DOK7 of breast cancer cells were much lower than MCF-10A cells by qRT-PCR assay." (PMID 33552156, 2021). "From above results, MCF-7 and SUM-1315 cells had the highest DOK7 expression among all breast cancer cells; we deleted DOK7 expression by transfecting with shRNAs in these two cell lines." (PMID 33552156, 2021). "To inquire the relationship between the levels of DOK7 and the clinical features of breast cancer patients, we compared the mRNA levels of DOK7 in 68 paired normal and breast cancer tissues." (PMID 33552156, 2021). "Here, for the first time, we exhibited that DOK7 expression reduced in breast cancer tissues and lower levels of DOK7 were related to more aggressive clinical behaviors and worse prognosis of breast cancer." (PMID 33552156, 2021). "DNA hypermethylation of DOK7 had been detected in breast cancer samples, including blood, tumor tissues, and cultured cells, and it is considered to be one of the downregulation mechanisms in DOK7 expression." (PMID 33552156, 2021). "Repression of PTEN expression by PTEN siRNAs or SF1670 (PTEN inhibitor) rescued the tumor-inhibiting effect of DOK7 overexpression, suggesting that DOK7 inhibits proliferation, migration, and invasion of breast cancer cells though the PI3K/PTEN/AKT pathway." (PMID 33552156, 2021). "In matched breast tissue pairs obtained from 68 breast cancers, DOK7 expression was obviously decreased in tumors." (PMID 33552156, 2021). "The results showed that the breast cancer tissues of the higher stage (III/IV stage) expressed significantly lower levels of DOK7 than those of I/II stage subgroups." (PMID 33552156, 2021). "On the contrary, knocking down the expression of DOK7 promoted the malignancy in breast cancer cells in vitro." (PMID 33552156, 2021). "Taken together, these data presented that the elevated expression of DOK7 is crucial for inhibiting tumor progression and metastasis of breast cancer." (PMID 33552156, 2021). "Patients with lower levels of DOK7 had worse overall survival (OS) (P < 0.001) in 626 breast cancer patients (314 samples in low levels of DOK7 and 312 samples in high levels of DOK7)." (PMID 33552156, 2021). "Specifically, we confirmed that the low levels of DOK7 were related to bad clinical outcomes and poor prognosis of patients with breast cancer; therefore, DOK7 had a potential value as a molecular biomarker in prognosis prediction of breast cancer." (PMID 33552156, 2021). "Overexpression of DOK7 inhibited proliferation, migration, and invasion, while silencing DOK7 expression promoted the malignancy of breast cancer." (PMID 33552156, 2021).
breast carcinoma (continued). "MDA-MB-231 and SKBR3 cells had lowest DOK7 expression among all breast cancer cells, so we overexpressed DOK7 in these two cell lines." (PMID 33552156, 2021). "All these data suggested that low levels of DOK7 resulted in a bad prognosis in breast cancer patients." (PMID 33552156, 2021). "In our recent findings, we displayed that the expression of DOK7 was remarkably reduced in clinical breast cancer tissues and the low levels of DOK7 were related to the bad clinical outcomes and prognosis in breast cancer patients." (PMID 33552156, 2021). "In breast cancer, DOK7 suppresses the cell growth and mobility by targeting PI3K/AKT pathway." (PMID 38095644, 2023). "In breast cancer, DOK7 overexpression could suppress the cell proliferation and mobility by dampening phosphoinositide 3-kinase (PI3K)/Protein kinase B (AKT) signaling pathway." (PMID 38095644, 2023). "Because of DOK7 could inhibit breast cancer cell invasion and migration ability via PI3K/PTEN/AKT pathway, and our result showed a similar pathway." (PMID 36709279, 2023). "In this study, we clarified the effects of DOK7 in breast cancer." (PMID 33552156, 2021). "In addition, the overexpression of DOK7 inhibits proliferation, invasion, and migration of breast cancer." (PMID 33552156, 2021). "Finally, to investigate the possible signaling mechanism, we first found that the level of p-AKT protein was extremely downregulated and the level of PTEN protein was remarkably upregulated after overexpressing DOK7 in breast cancer cells." (PMID 33552156, 2021). "On the contrary, knocking down DOK7 expression promoted the malignancy of breast cancer." (PMID 33552156, 2021). "Similarly, higher levels of DOK7 had better distant metastasis-free survival (DMFS) than those with low DOK7 expression (P < 0.0001) in 664 breast cancer patients (333 samples in low levels of DOK7 and 331 samples in high levels of DOK7)." (PMID 33552156, 2021). "DOK7 is also associated with malignancy of several types of cancer, including breast cancer, where DOK7 can inhibit cell proliferation, migration, and invasion of breast cancer by mediating signals through the PI3K/PTEN/AKT pathway, and thus, may act as a tumor suppressor gene." (PMID 35976950, 2022). "It has been reported that there were significant DOK7, VIM, and CXCR4 hypo methylations in a sub population of Iranian breast cancer cases compared with normal subjects." (PMID 33883026, 2021). "Another reports also showed DOK7 and VIM hyper methylations in Spanish and Australian breast cancer patients, respectively." (PMID 33883026, 2021). "We demonstrated that DOK7 inhibits proliferation, migration, and invasion via the PI3K/PTEN/AKT pathway in breast cancer cells." (PMID 33552156, 2021). "Recent studies have revealed that the DOK7 gene and its family are closely related to the initiation and development of many malignant tumors, such as lung cancer, breast cancer, and leukemia [28, -30], but the detailed mechanism has not been fully understood." (PMID 34528912, 2021). "However, the connection between the levels of DOK7 and the initiation of breast cancer has not been assessed yet." (PMID 33552156, 2021). "In addition, DOK7 depletion significantly promoted the cell growth of MCF7 and SUM-1315 cells compared with the control groups was found using CCK8 assay, suggesting that silencing DOK7 expression promoted cellular growth of breast cancer cells in vitro." (PMID 33552156, 2021).
lung cancer (5 papers, 2021 to 2023). A malignant neoplasm involving the lung. "For example, DOK7 was found to be down-regulated in lung cancer and its reduced expression was associated with the poor survival in lung cancer patients." (PMID 38095644, 2023). "Previous studies demonstrated that DOK7 was downregulated in a variety of cancer tissues and low levels of DOK7 closely linked to poor prognosis in lung cancer patients." (PMID 33552156, 2021). "In lung cancer, lower DOK7 expression was associated with lower survival." (PMID 36551712, 2022). "In agreement with our data, DOK7 was reported as a tumor suppressor in glioma, breast and lung cancer." (PMID 38095644, 2023). "Only one study confirmed that DOK7 was greatly under-expressed in lung cancer, and DOK7 overexpression suppressed the proliferation and migration of lung cancer cells." (PMID 34528912, 2021). "A recent study has showed that the low level of DOK7 was responsible for poor prognosis in lung cancer patients and DOK7 played an important role on cell growth, migration, and invasion." (PMID 33552156, 2021). "DOK7 is closely related to malignant cancers, including lung cancer and glioma." (PMID 33552156, 2021).
myasthenia (5 papers, 2014 to 2026). "Thus, since DOK7 myasthenia is recessive, the heterozygous mutation found in this gene was also considered unlikely to be causative." (PMID 29441694, 2018). "For example, genetic muscle-specific restoration of DOK7 rescued motor function and improved survival in DOK7 myasthenia mice." (PMID 37637210, 2023). "Enlarged motor endplates have been demonstrated in response to AAV9-delivered DOK7 in an Smn2B/– model of SMA, DOK7 myasthenia, and Emery Dreifuss muscular dystrophy." (PMID 37637210, 2023). "For example, in one representative prior study, such an AAV9 vector was used to overexpress DOK7 in a model of DOK7 myasthenia, with mice reported to survive more than 1 year with no apparent abnormality." (PMID 37637210, 2023). "Although most of the patients with mutations in established CMS genes (such as DOK7, MUSK, RAPSYN, CHRNA1, CHRNB1, CHRND, and CHRNE) do not show cognitive symptoms, in some newly identified CMS subtypes, myasthenia is only one element of a more severe and complex clinical spectrum." (PMID 41575592, 2026). "By contrast, we previously showed that DOK7 gene therapy greatly facilitates NMJ enlargement in the appropriate central region of myofibers without lethal effects for more than 1 year in DOK7 myasthenia model mice, suggesting that DOK7 gene therapy is a safer therapeutic approach." (PMID 28490573, 2017). "Moreover our mouse model does not mimic the congenital (Dok-7 or ColQ) myasthenias where clear strength gains have been reported in patients following treatment with albuterol or ephedrine." (PMID 24505322, 2014).
amyotrophic lateral sclerosis (3 papers, 2020 to 2024). Amyotrophic lateral sclerosis (ALS) is a neurodegenerative disease characterized by progressive muscular paralysis reflecting degeneration of motor neurons in the primary motor cortex, corticospinal tracts, brainstem and spinal cord. "Moreover, DOK7 gene therapy suppressed denervation at NMJs and enhanced motor activity and life span in a mouse model of familial amyotrophic lateral sclerosis (ALS), a fatal neuromuscular disease with motor neuron degeneration." (PMID 32758427, 2020). "Moreover, therapeutic administration of an adeno-associated virus vector encoding human Dok-7 (DOK7 gene therapy) suppressed muscle denervation and enhanced motor activity in a mouse model of amyotrophic lateral sclerosis (ALS)." (PMID 32758427, 2020).
glioma (3 papers, 2021 to 2023). A benign or malignant brain and spinal cord tumor that arises from glial cells (astrocytes, oligodendrocytes, ependymal cells). "For instance, DOK7 was found to be down-regulated in glioma and its down-regulation facilitates the growth of glioma cells." (PMID 38095644, 2023). "Another study also showed that silencing the expression of DOK7 significantly inhibited the development of glioma both in cells and in animal models." (PMID 33552156, 2021). "Similarly, DOK7 was found to be downregulated in glioma, and its overexpression inhibited both in vitro and in vivo proliferation of glioma cells." (PMID 36551712, 2022). "In glioma, DOK7 expression was repressed by DNMT1 and DOK7 down-regulation facilitates the proliferation of glioma cells." (PMID 38095644, 2023).
sarcopenia (3 papers, 2021 to 2024). Progressive decline in muscle mass due to aging which results in decreased functional capacity of muscles. "LMHFV attenuated NMJ degeneration and sarcopenia progression by increasing Dok7 expression through suppressing ERK1/2 phosphorylation in skeletal muscle." (PMID 38532712, 2024). "LMHFV may attenuate NMJ degeneration and sarcopenia progression by increasing Dok7 expression through suppressing ERK1/2 phosphorylation." (PMID 38532712, 2024). "Our findings suggest that LMHFV could mitigate NMJ degeneration and sarcopenia progression by increasing Dok7 expression through suppressing ERK1/2 phosphorylation in skeletal muscle." (PMID 38532712, 2024). "Additionally, further animal studies investigating Dok7 and ERK1/2 phosphorylation regulation were needed to solidify the conclusion that LMHFV could attenuate the progress of sarcopenia and NMJ degeneration by increasing Dok7 expression through suppressing ERK1/2 phosphorylation." (PMID 38532712, 2024).